ABHD3 (abhydrolase domain containing 3, phospholipase)
Description:
Phospholipase that may play a role in phospholipids remodeling. May selectively cleave myristate (C14)-containing phosphatidylcholines through its predominant phospholipase 1 activity, cleaving preferentially acyl groups in sn1 position. In parallel, may have a minor phospholipase 2 activity acting on acyl groups in position sn2. In addition to (C14)-containing phosphatidylcholines, may also act on other medium-chain-containing and oxidatively truncated phospholipids.
Synonyms: LABH3
Tractability: Antibody: its Gene Ontology location is reachable by antibodies, with high confidence; UniProt predicts a signal peptide or a membrane-spanning region; the Human Protein Atlas places it where antibodies can reach. PROTAC: ubiquitination databases record sites on it.
Gene: Protein-coding gene on chromosome 18 (21,650,898 to 21,704,808, reverse strand). Ensembl gene ENSG00000158201.
Subcellular location: Membrane
Subcellular location (Human Protein Atlas): Nucleoplasm; Plasma membrane; Vesicles
Pathways (Reactome):
Metabolism: Synthesis of PC
Gene Ontology:
Molecular function: phospholipase A1 activity; phospholipase A2 activity; acetylesterase activity; monoacylglycerol lipase activity; 1-alkyl-2-acetylglycerophosphocholine esterase activity
Biological process: phosphatidylcholine metabolic process; medium-chain fatty acid biosynthetic process; medium-chain fatty acid catabolic process; phosphatidylcholine biosynthetic process
Cellular component: plasma membrane; membrane
Genetic constraint (gnomAD): Loss-of-function variants: 46 observed, 48.58 expected, observed/expected ratio (o/e) 0.95, 90% interval 0.75 to 1.21. The upper end of that interval is the gene's LOEUF score, 1.21, which puts it in group 5 of 6, group 1 being the genes least tolerant of losing a copy. Missense variants: 490 observed, 493.6 expected, observed/expected ratio (o/e) 0.99, 90% interval 0.92 to 1.07. Synonymous variants: 192 observed, 179.4 expected, observed/expected ratio (o/e) 1.07, 90% interval 0.95 to 1.21.
Homologues: Orthologues: chimpanzee ABHD3 (99% identical), macaque ABHD3 (98% identical), dog ABHD3 (96% identical), rat Abhd3 (93% identical), mouse Abhd3 (92% identical), pig ABHD3 (86% identical), rabbit ABHD3 (85% identical), guinea pig ABHD3 (84% identical), tropical clawed frog abhd3 (68% identical), zebrafish abhd3 (67% identical), Drosophila melanogaster Hydr1 (39% identical), Caenorhabditis elegans abhd-3.1 (29% identical), and 1 more. Paralogues in human: ABHD1 (43% identical), ABHD2 (24% identical), ABHD15 (23% identical).
Diseases named in the same sentence as ABHD3 in open-access papers:
ABHD3 is named in the same sentence as 6 diseases in open-access papers, as found by Europe PMC text mining. Sharing a sentence is not in itself a finding about the gene and the disease. The quoted sentences say what the papers report.
autism (1 paper, 2019). Persistent deficits in social interaction and communication and interaction as well as a markedly restricted repertoire of activity and interest as well as repetitive patterns of behavior. "In a screen of 135 genes in the adult mouse (selected for high cerebellar expression or prior association with autism), we identified only three (Abhd3, Lrp8, and Plcβ4) with a somewhat similar lobular expression pattern to Spry3, and none that recapitulated the p75NTR expression pattern." (PMID 31275178, 2019).
breast carcinoma (1 paper, 2011). "Abhydrolase domain-containing protein 3 (Abhd3) is upregulated in breast cancer tumours." (PMID 21966401, 2011).
ABHD3 also shares sentences with these, for which no sentence is quoted: cancer (2 papers); Hepatic fibrosis (1); neuropathy (1); tumours (1).